INS (insulin)
Diseases named in the same sentence as INS in open-access papers (continued):
Sharing a sentence is not in itself a finding about the gene and the disease.
diabetes (continued). "**Diabetes medication included insulin and/or medication to lower blood sugar." (PMID 41039901, 2025). "The parents of boys with diabetes believed that their sons were more neutral (3.02) in their attitude toward physical activity when they switched from MDIs (multiple daily injections) to an insulin pump." (PMID 40426791, 2025). "A previous study involving community-dwelling old women without known diabetes, found that frailty was associated with impaired responses to glucose loading, indicating compromised glucose-insulin regulation." (PMID 41044677, 2025). "For example, in the “EMPOWER-D” study, participants could record diabetes-relevant data through an online platform, which included details on dietary habits, physical exercise, home blood pressure measurements, insulin administration, and body weight." (PMID 40051514, 2025). "This qualitative study employed focus group discussions (FGDs) with 30 participants, including adults, adolescents, and caregivers managing insulin-requiring diabetes, conducted between May and September 2023 in Kuala Lumpur and Putrajaya, Malaysia." (PMID 39910989, 2025). "One of the key diabetes-related defects in skeletal muscle is impaired insulin signaling." (PMID 40806520, 2025). "However, the regulation of insulin levels and the health effects of insulin are manly studied in the metabolic context of obesity and diabetes research." (PMID 40643485, 2025). "Some older people with diabetes may have reduced endogenous insulin secretory capacity owing to age or other reasons, and treatment with LIs plus RIs or LIs plus diabetes drugs other than insulin is thus often selected." (PMID 40777704, 2025). "Diabetes mellitus (DM) is a chronic metabolic disorder characterized by disruptions in the metabolism of carbohydrates, lipids, and proteins, primarily due to inadequate insulin secretion or insulin resistance in target cells." (PMID 40757164, 2025). "The lack of insulin-secreting β-cells is the major hallmark of diabetes leading to glucose intolerance and sustained hyperglycemia." (PMID 40014427, 2025). "Diabetes mellitus (DM) comprises a group of metabolic disorders characterized by chronically elevated blood glucose levels due to insufficient insulin production, impaired insulin action, or a combination of both." (PMID 40806023, 2025). "Evaluation of endogenous insulin secretion, particularly outside the honeymoon period may improve diabetes management in cases where decisions regarding treatment with insulin injections have to be made." (PMID 40587435, 2025). "This affects insulin sensitivity and plays a role in the development of diabetes." (PMID 39792715, 2025). "Likewise, the oligomerization of the glucagon-like peptide-1 receptor (GLP-1R) with the glucose-dependent insulinotropic polypeptide receptor (GIPR) in regulating post-endocytic insulin secretion offers a promising new approach for diabetes treatment." (PMID 40362321, 2025). "Fourteen of the countries had >100 people reporting insulin use for diabetes." (PMID 40245017, 2025). "Diabetes mellitus (DM) is a chronic metabolic disorder characterized by impaired metabolism of carbohydrates, lipids, and proteins due to defects in insulin secretion, insulin action, or both." (PMID 40943614, 2025). "Since wearing a CGM, I take my diabetes pills, insulin or both at the right time and as prescribed." (PMID 40409747, 2025). "Additionally, 89 physicians (32.1%) reported awareness of travel safety recommendations for patients with diabetes, and 45 physicians felt confident about how to adjust insulin doses for patients traveling across multiple time zones (16.2%)." (PMID 40901237, 2025). "Hyperglycemia arises from a multifactorial etiology involving genetic, environmental, and behavioral factors and is primarily driven by impaired insulin secretion, impaired insulin action, or a combination of both, with variations across different types of diabetes." (PMID 40407447, 2025).
diabetes (continued). "Moreover, many Ericaceae species have a long history of ethnomedicinal use in glycemic control; for example, bilberry (Vaccinium myrtillus) leaf infusions were widely used as a traditional remedy for diabetes before the advent of insulin therapy." (PMID 40430501, 2025). "Diese Faktoren zusammen mit bestehendem Diabetes mellitus oder einer Insulin-Resistenz kann zu einer nicht kontrollierten diabetischen Stoffwechsellage führen trotz maximaler Reduktion der Glucosemenge in den Ernährungsbeuteln und zuckersenkender Medikamente inklusive injiziertem Insulin." (PMID 40360142, 2025). "It was shown that the blood glucose level in the group of diabetes plus CA decreased by 17.09% on the 30th day compared to the diabetes group, which may be related to increased insulin secretion and the peripheral use of glucose." (PMID 40722869, 2025). "This impacts insulin secretion and blood glucose regulation, potentially leading to diabetes." (PMID 40123888, 2025). "Future studies should explicitly differentiate diabetes subtypes, particularly insulin‐dependent versus non‐insulin‐dependent diabetes, as these subgroups may have different risk profiles and outcomes." (PMID 40351235, 2025). "However, when survival was analyzed according to key factors of diabetes, including disease duration and insulin use, significant differences were observed." (PMID 41464593, 2025). "Further, misinformation may also be shared across family members in how to manage diabetes with actual sharing of supplies (e.g., insulin, glucose strips) with potential benefits as well as liabilities associated with such sharing." (PMID 41051982, 2025). "In addition to improving insulin production, targeting key enzymes involved in carbohydrate metabolism represents a promising strategy for diabetes management." (PMID 41142063, 2025). "Also, disruptions in insulin secretion in rodents initiate diabetes, suggesting a strong link between the circadian timing system and pancreatic beta cell function." (PMID 40906096, 2025). "In this study, we performed sex‐stratified observational and MR analyses to evaluate the sex‐specific associations of diabetes and glycaemic traits with the risk of different CVD outcomes, which were accompanied by MR analyses on the effect of fasting glucose and insulin." (PMID 40259500, 2025). "Furthermore, L-arginine supports growth hormone secretion, aids muscle protein synthesis, and has been found to transform pancreatic cells into insulin-producing cells, potentially reversing diabetes-related effects." (PMID 40361585, 2025). "Impaired kidney function often is associated with alterations in insulin dynamics, glucose tolerance, and glucose homeostasis, even in people without diabetes." (PMID 41163811, 2025). "Nanomedicine-based solutions, such as trace element nanoparticles for insulin delivery and immune modulation, may provide non-invasive, highly effective therapies for diabetes management." (PMID 40217595, 2025). "Diabetes typically begins with the development of insulin resistance; cells may initially compensate for this resistance by secreting more insulin, which can prevent hyperglycemia." (PMID 39906623, 2025). "When splitting diabetes into sub-groups, the decreased all-cause mortality risk was only present in the “non-insulin GLD only” and “insulin and non-insulin GLD” subgroups." (PMID 41350985, 2025). "Likewise, substantial genetic determinants of metabolic diseases, including diabetes, obesity, and hypercholesterolemia, influence insulin signaling, lipid metabolism, and energy balance." (PMID 40430848, 2025). "Caregivers described potential uses for the app at home, including reviewing glucose patterns and adjusting insulin doses, staying connected with their diabetes healthcare team, reviewing resources, and organizing information and tasks related to clinical visits." (PMID 41171736, 2025).
diabetes (continued). "Hence, it’s crucial for individuals with diabetes to manage infections promptly, monitor blood glucose levels closely, and adjust insulin doses as needed during illness to prevent the development of diabetic ketoacidosis." (PMID 39847589, 2025). "The standard treatment for pediatric patients with diabetes involves the use of exogenous insulin." (PMID 40215252, 2025). "Patients with DR had a longer duration of diabetes and a higher frequency of diabetes treatment (both oral medication and insulin treatment); higher SBP, HbA1c levels, and fasting glucose levels; and lower total cholesterol, AST, and hemoglobin levels compared to those without DR." (PMID 39891252, 2025). "Dysregulation of zinc transporter proteins can lead to impaired insulin activity and increased oxidative stress, contributing to the development of insulin resistance and beta-cell dysfunction, both of which are key factors in the etiology of diabetes." (PMID 39941463, 2025). "This suggests that METTL14 might influence insulin signaling transduction to enhance diabetes by regulating the expression of TPK1, IPMK, and PIK3R1." (PMID 40299682, 2025). "Furthermore, studies have shown that diabetes impairs insulin signaling in fibroblasts, resulting in delayed wound healing." (PMID 41387944, 2025). "This reduces insulin sensitivity, promotes ceramide accumulation, and increases β-cell apoptosis, ultimately exacerbating insulin resistance and contributing to the development of diabetes and diabetic retinopathy." (PMID 41345744, 2025). "Furthermore, its low glycemic index and high fiber content aid in blood sugar regulation by increasing insulin production and utilization, benefiting individuals with diabetes." (PMID 40724606, 2025). "Our findings are likely to apply to any person with diabetes who uses subcutaneous insulin." (PMID 40324886, 2025). "When PwT2D understood that diabetes is progressive and they may eventually require insulin, they appreciated the necessity of insulin." (PMID 40171977, 2025). "Moreover, curcumin demonstrates significant therapeutic potential in the management of diabetes by improving glucose and lipid metabolism, enhancing insulin sensitivity, and reducing insulin resistance in experimental animal models of diabetes." (PMID 40864768, 2025). "This may be due to the viral destruction of insulin-producing β cells or the infection of adipose cells, resulting in enhanced insulin resistance as can be observed with the large doses of insulin sometimes required to manage hospital patients with diabetes." (PMID 40804810, 2025). "The study found that participants using the AI application achieved optimal insulin dosing more quickly, exhibited higher insulin adherence, experienced better glycemic control, and reported reduced diabetes‐related emotional distress compared to those receiving standard care." (PMID 40309616, 2025). "Furthermore, ALOX12 has an important function in obesity-related complex phenotypes, including hypertension, atherosclerosis, diabetes and insulin secretion, and obesity itself." (PMID 40149853, 2025). "In addition, PPARγ agonists can effectively treat diabetes and lipid metabolism disorders as insulin sensitizers." (PMID 41011216, 2025). "Additionally, the strong expression of miR-185-5p in metabolic and endocrine-related tissues supports its involvement in glucose metabolism and insulin signaling, indicating its relevance in the pathophysiology of diabetes mellitus." (PMID 40282289, 2025). "This suggests that mitochondrial dysfunction could contribute to the development of diabetes, which often results from an imbalance in glucose metabolism and insulin secretion." (PMID 39835172, 2025). "The mean diabetes duration for type 1 diabetes was 14.4 ± 8.9 years, with a range of 2.0 to 41.0 years, the mean BMI was 26.7 ± 6.5 kg/m2 (range = 18.7–57.8 kg/m2), and the distribution of diabetes medications was 94.9% (n = 94) insulin and 5.1% (n = 5) insulin and oral medication(s)." (PMID 41329697, 2025).
diabetes (continued). "In summary, the current research demonstrated that the chronic administration of Cg and Ec, two plants traditionally used in the treatment of diabetes, improve glucose homeostasis, particularly increasing glucose and insulin tolerance, decreasing IR, and optimizing insulin secretion." (PMID 41155548, 2025). "Median diabetes duration was 22 years and duration of insulin pump treatment was 11 years." (PMID 39172172, 2025). "The interplay between insulin and nitric oxide (NO) in the regulation of vascular resistance has been extensively studied in other forms of diabetes, with reports dating back to the 1990s documenting impaired endothelium-dependent vasodilation in patients with insulin-dependent diabetes mellitus." (PMID 41373661, 2025). "As mitochondrial fission is increased in diabetes and contributes to circulating insulin levels, fission protein 1 expression mitigated by elevated miR-484 levels may lead to reduced glucose metabolism deregulation." (PMID 39857744, 2025). "Challenges for staff managing diabetes care in an acute environment include having an inadequate knowledge of diabetes management and insulin administration devices, meeting patient self‐management needs, and facing operational pressures and the time required to provide holistic care." (PMID 41358572, 2025). "Numerous studies have reported the anti-diabetic effects of tea polyphenols in experimental diabetes models, demonstrating their ability to lower blood glucose levels, improve insulin sensitivity, and reduce oxidative stress and inflammation associated with type 2 diabetes mellitus." (PMID 41256860, 2025). "Additionally, previous studies have shown that genistein regulates insulin and glucose metabolism, aiding in the treatment of diabetes in postmenopausal women and diabetic animal models." (PMID 40028534, 2025). "Therefore, after a diabetes diagnosis, oral metformin should be avoided, and insulin therapy should be initiated as early as possible." (PMID 40520227, 2025). "ARF39, INM13’s mother, UKF35, and UKM22 described a certain routine and mentioned how some key events of daily life, e.g., waking up, eating breakfast, or going to school, lead to some aspect of managing diabetes, such as testing blood glucose or taking insulin." (PMID 40565407, 2025). "Because of the plethora of insulin-mediated effects on target-organs and tissues, diabetes may enhance other secondary complications in organs and tissues like the kidneys, liver, skeletal muscle, retina, heart, and adipose tissues." (PMID 40559375, 2025). "Olive oils with higher concentrations of oleic acid may better influence lipid metabolism and insulin sensitivity, potentially making them more beneficial for cardiovascular health and metabolic conditions like diabetes." (PMID 39940428, 2025). "Type 2 diabetes mellitus (T2DM) is a chronic metabolic disorder characterized by impaired insulin secretion, peripheral insulin resistance, and hyperglycemia, which together contribute to microvascular and macrovascular complications, reduced quality of life, and increased mortality." (PMID 41295324, 2025). "Furthermore, advancements in wearable insulin biosensors that combine real-time glucose monitoring with automated insulin delivery are enhancing glycemic control and quality of life for diabetes patients." (PMID 40979718, 2025). "Some of these proteins and metabolites were found to be related to diabetes and insulin secretion." (PMID 41550874, 2025). "IR isdefined as the reduced efficiency of insulin in promoting glucose uptake and glucoseutilization and can promote the progression of diabetes by inducing an imbalance inglucose metabolism, altering lipid metabolism in the whole body and causingendothelial dysfunction." (PMID 40232167, 2025).
diabetes (continued). "Furthermore, quality of life can also be affected by the presence of complications of diabetes, socioeconomic status, psychosocial support, glycemic control levels, comorbidities as well as use of insulin vs oral hypoglycemic agents." (PMID 40103901, 2025). "Therefore, a desired goal of diabetes management still involves achieving effective and secure insulin sensitivity." (PMID 39906612, 2025). "Type 1 diabetes mellitus (T1DM) is a chronic and progressive autoimmune disorder characterized by severe destruction of pancreatic β cells, leading to an absolute deficiency of insulin and subsequent hyperglycemia." (PMID 39792010, 2025). "Additionally, our data revealed disparities in access to diabetes technologies among people with diabetes undergoing haemodialysis and treated with insulin." (PMID 38859547, 2025). "However, the measurement of the fasting insulin and the calculation of the HOMA-IR and HOMA-β were essential for identifying subjects with diabetes requiring insulin therapy because of deficiency with low production, as seen in our large population." (PMID 40218874, 2025). "Diabetes, a debilitating metabolic condition marked by chronic hyperglycemia due to faulty insulin production and/or action, has become one of the rapidly escalating global health crises of the 21st century and the eighth leading cause of death and disability worldwide." (PMID 40747186, 2025). "Additionally, promoting regular physical activity can enhance metabolic health, reduce the risk of diabetes, and mitigate CKM-exacerbating factors by improving glucose metabolism and insulin sensitivity." (PMID 41516982, 2025). "In the US cohort, the rate of insulin use among diabetes patients was significantly higher, and this treatment approach may weaken the predictive efficacy of the TyG index for sarcopenia by improving insulin resistance." (PMID 41048435, 2025). "In diabetes, it plays a role in insulin regulation and blood sugar control." (PMID 40390089, 2025). "Therefore, there is a need to develop tailored diabetes management programs specifically for insulin users in this demographic." (PMID 40471961, 2025). "Under normal renal function, glucose is reabsorbed efficiently below a threshold that is frequently exceeded in diabetes, leading to glycosuria; alterations in renal glucose handling have been associated with urinary KIM-1 and the renal glucose threshold in insulin-resistant states." (PMID 41155478, 2025). "Thus, hPSC-derived pancreatic pseudoislets also known as autologous iPSC-derived β cells potentially offer an alternative inexhaustible source of insulin-producing β-cells for potential diabetes therapy in the future." (PMID 39883142, 2025). "The favorable impact of other diabetes medications, such as insulin, sulfonylureas, and DPP-IV inhibitors, on aneurysm progression remains unclear due to the limited number of small-scale studies." (PMID 40566116, 2025). "Also, automated insulin delivery technologies that promise to drastically improve T1D outcomes are expensive and require diabetes team support for success." (PMID 39294242, 2025). "Additionally, there is a distinction between curative medications, such as insulin for diabetes management and preventive medications like statins for cholesterol reduction or glucagon-like peptide-1 (GLP-1) receptor agonists like ozempic for weight reduction." (PMID 40961920, 2025). "Fourth, diabetes type was defined using diagnosis codes, which may misclassify insulin-treated type 2 diabetes as type 1." (PMID 41536836, 2025). "It summarizes the main biochemical pathways, cellular mechanisms, and molecular interactions that highlight both the function of TIM and its implications in diabetes pathophysiology, particularly focusing on its regulatory role in glucose metabolism and insulin secretion." (PMID 41009376, 2025).